PSPC1 (paraspeckle component 1)
Description:
RNA-binding protein required for the formation of nuclear paraspeckles. Binds to poly(A), poly(G) and poly(U) RNA homopolymers. Regulates, cooperatively with NONO and SFPQ, androgen receptor-mediated gene transcription activity in Sertoli cell line (By similarity). Regulates the circadian clock by repressing the transcriptional activator activity of the CLOCK-BMAL1 heterodimer (By similarity). Plays a role in the regulation of DNA virus-mediated innate immune response by assembling into the HDP-RNP complex, a complex that serves as a platform for IRF3 phosphorylation and subsequent innate immune response activation through the cGAS-STING pathway.
Synonyms: PSP1; FLJ10955
Tractability: PROTAC: ubiquitination databases record sites on it; its protein half-life has been measured.
Gene: Protein-coding gene on chromosome 13 (19,674,752 to 19,783,019, reverse strand). Ensembl gene ENSG00000121390.
Subcellular location: Nucleus speckle; Nucleus, nucleolus; Nucleus matrix; Cytoplasm
Subcellular location (Human Protein Atlas): Nucleoplasm; Nucleoli fibrillar center
Gene Ontology:
Molecular function: protein binding; RNA binding; nucleic acid binding
Biological process: activation of innate immune response; membraneless organelle assembly; negative regulation of DNA-templated transcription; regulation of circadian rhythm; regulation of DNA-templated transcription
Cellular component: fibrillar center; nuclear speck; nucleoplasm; paraspeckles; RNA polymerase II transcription regulator complex; cytoplasm; nuclear matrix; nucleus; nucleolus
Genetic constraint (gnomAD): Loss-of-function variants: 10 observed, 35.59 expected, observed/expected ratio (o/e) 0.28, 90% interval 0.17 to 0.48. The upper end of that interval is the gene's LOEUF score, 0.48, which puts it in group 2 of 6, group 1 being the genes least tolerant of losing a copy. Missense variants: 381 observed, 588.39 expected, observed/expected ratio (o/e) 0.65, 90% interval 0.6 to 0.7. Synonymous variants: 177 observed, 212.59 expected, observed/expected ratio (o/e) 0.83, 90% interval 0.74 to 0.94.
Homologues: Orthologues: macaque PSPC1 (99% identical), dog PSPC1 (99% identical), mouse Pspc1 (98% identical), rat Pspc1 (98% identical), pig PSPC1 (97% identical), guinea pig PSPC1 (97% identical), chimpanzee PSPC1 (97% identical), rabbit PSPC1 (94% identical), tropical clawed frog pspc1 (78% identical), zebrafish pspc1 (67% identical). Paralogues in human: SFPQ (55% identical), NONO (54% identical), SPEN (24% identical), RAVER1 (16% identical), RBM15 (16% identical), RAVER2 (15% identical), RBM15B (13% identical).
Diseases named in the same sentence as PSPC1 in open-access papers:
PSPC1 is named in the same sentence as 28 diseases in open-access papers, as found by Europe PMC text mining. Sharing a sentence is not in itself a finding about the gene and the disease. The quoted sentences say what the papers report.
hepatocellular carcinoma (8 papers, 2019 to 2025). A malignant tumor that arises from hepatocytes. "Paraspeckle component protein PSPC1 is found to be upregulated in breast cancer, lung cancer, nasopharyngeal cancer and hepatocellular carcinoma along with pancreatic cancer." (PMID 41023804, 2025). "PSPC1 is also a substrate of protein tyrosine kinase 6 (PTK6) but sequestered PTK6 in the nucleus and abolished the PSPC1 oncogenic functions in human hepatocellular carcinoma (HCC) cells." (PMID 32570949, 2020). "Here, the authors demonstrate that PSPC1 is the contextual determinant of the oncogenic switch of PTK6/β-catenin subcellular localizations to drive metastasis of hepatocellular carcinoma cells via a PSPC1/PTK6/β-catenin signaling." (PMID 31844057, 2019). "Literature suggests that PSPC1 interacts with β-Catenin and maintains the nuclear retention of β-Catenin to promote the transcription of EMT and metastasis-related genes via wnt-β-Catenin pathway in hepatocellular carcinoma." (PMID 41023804, 2025). "For instance, PSPC1 was recently shown to be the contextual determinant of the TGF-β prometastatic switch and PTK6/β-catenin reciprocal oncogenic nucleocytoplasmic shuttling during hepatocellular carcinoma (HCC) progression." (PMID 34340703, 2021).
breast carcinoma (6 papers, 2014 to 2025). "Recent studies reported that PSPC1 was associated with various cancers, such as liver cancer, nasopharyngeal cancer, lung cancer and breast cancer, which is a poor prognostic factor for patient survival." (PMID 38069409, 2023). "The paraspeckle component 1 (PSPC1)-Sec1 family domain containing 2 (SCFD2)-DDIAS axis is highly expressed in tamoxifen-resistant breast cancer and is a potential diagnostic and therapeutic target for estrogen receptor (ER)-positive breast cancer." (PMID 37121974, 2023). "The PSPC1-High group (≥median) exhibited a higher recurrence risk than that of the PSPC1-Low group (<median) in two data sets of patients with breast cancer." (PMID 38069409, 2023). "Next, to examine the clinical significance of PSPC1 in breast cancer, we performed immunohistochemical analysis of PSPC1 in 114 ER-positive breast cancer samples." (PMID 35681031, 2022). "DDIAS may be a potential therapeutic target for tamoxifen-resistant breast cancer since the inhibition of PSPC1 or SCFD2 reduces in vivo tumor development in tamoxifen-resistant breast cancer." (PMID 37121974, 2023). "In conclusion, the present results suggest that PSPC1 would facilitates hormone-dependent breast cancer proliferation by exhibiting RNA processing of ESR1 and SCFD2, the latter further contributes to anti-apoptotic or proliferative responses by modulating the expression of DDIAS and MYBL1." (PMID 35681031, 2022). "Studies in recent years have demonstrated that PSPC1 was overexpressed in liver cancer, nasopharyngeal cancer, lung cancer and breast cancer, which is a negative prognostic factor for patient survival." (PMID 36894530, 2023).
colorectal cancer (4 papers, 2023 to 2025). A primary or metastatic malignant neoplasm that affects the colon or rectum. "Similar findings were also shown by another report where lncRNA LOC105369504 alters PSPC1 protein expression in colorectal cancer." (PMID 41023804, 2025). "In a recent study, a novel lncRNA LOC105369504 was identified, which was found to be a potential functional lncRNA having tumor suppressive as well as antimetastatic activity in colorectal cancer cells by regulating the protein of paraspeckles compound 1 (PSPC1)." (PMID 40176927, 2024).
Obesity (2 papers, 2025 to 2026). Accumulation of substantial excess body fat. "Loss of PSPC1 expression in adipose tissue in vivo compromised adipocyte development and lipid storage and affected the development of diet-induced obesity and insulin resistance." (PMID 41596407, 2026). "It is reported that paraspeckle component 1 (PSPC1) promotes obesity by facilitating adipogenesis and enhancing fat storage." (PMID 40732992, 2025). "In addition, PSPC1 expression is significantly reduced in the white adipose tissue of animal models of obesity." (PMID 41596407, 2026). "Furthermore, in mice lacking PSPC1 specifically in adipose tissue, there is reduced fat mass and lipid storage, leading to resistance to diet-induced obesity and insulin resistance." (PMID 40732992, 2025).
viral infection (2 papers, 2017 to 2024). "This translocation suggests a potential shift in PSPC1 function during viral infection, as it primarily resides in the nucleus under normal conditions." (PMID 38793620, 2024). "PSPC1 has been known to move to the cytoplasm in response to a variety of cellular stresses; therefore, this translocation is expected during viral infection." (PMID 38793620, 2024). "Immunoblotting revealed that viral infection does not affect the expression of the paraspeckle protein components P54nrb and PSPC1 in HeLa cells." (PMID 27783096, 2017).
Acute Myeloid Leukaemia (1 paper, 2026). "To uncover convergent transcriptional processes in acute myeloid leukaemia (AML), we analysed differentially expressed genes (DEGs) across four perturbation models: PSPC1 knockdown, JMJD1C knockdown, RUNX1 knockdown, and venetoclax in conjunction with cysteine starvation (VEN + CSA)." (PMID 41492215, 2026).
Alzheimer disease (1 paper, 2025). A progressive, neurodegenerative disease characterized by loss of function and death of nerve cells in several areas of the brain leading to loss of cognitive function such as memory and language. "PSPC1 maintaining genome integrity during the DNA damage response decreased in Alzheimer’s disease research." (PMID 41327336, 2025).
gastric cancer (1 paper, 2025). A primary or metastatic malignant neoplasm involving the stomach. "To verify the functional role of PSPC1 in gastric cancer progression, we performed loss-of-function experiments in two gastric cancer cell lines, HGC-27 and AGS." (PMID 40959076, 2025). "Functional experiments showed that knockdown of PSPC1 significantly inhibited the proliferation (inhibition rate >50%, P <0.001) and migration ability (P<0.0001) of gastric cancer cells." (PMID 40959076, 2025). "CCK-8 results showed that PSPC1 knockdown significantly inhibited the proliferative ability of both gastric cancer cells." (PMID 40959076, 2025). "PSPC1 plays a key role in gastric cancer progression, and has the value of a potential therapeutic target." (PMID 40959076, 2025). "Although PSPC1 is associated with cell proliferation and metastasis in a variety of tumors, its specific mechanism in gastric cancer has not been previously elucidated." (PMID 40959076, 2025). "Taken together, these results indicate that PSPC1 plays an important role in promoting the proliferation and migration of gastric cancer cells, suggesting that it may act as a promoter of gastric cancer progression." (PMID 40959076, 2025). "Finally, based on the expression data of four gene markers (DACT1, EZH2, PAK2, PSPC1), we constructed a staging prediction model for 953 gastric cancer samples (319 early, 497 intermediate, and 137 advanced)." (PMID 40959076, 2025).
glioblastoma (1 paper, 2025). The most malignant astrocytic tumor (WHO grade IV). "In glioblastoma, NONO cooperates with PSPC1 to bind GPX1 pre-mRNA, regulating its alternative splicing and thereby influencing tumor growth, invasion, and redox homeostasis." (PMID 41174721, 2025). "In glioblastoma, NONO cooperatively binds to the intron region of GPX1 pre-mRNA with PSPC1, regulating the alternative splicing of GPX1, which affects tumor growth, invasion, and redox homeostasis." (PMID 41174721, 2025).
kidney cancer (1 paper, 2025). Primary or metastatic malignant neoplasm involving the kidney. "Notably, SFPQ, a close family member of NONO and PSPC1, has been identified as essential for the survival of both TFE3 fusion and non-fusion kidney cancer cells." (PMID 41027885, 2025).
melanoma (1 paper, 2021). A malignant, usually aggressive tumor composed of atypical, neoplastic melanocytes. "To determine a potential synergistic effect, we selected OSA plasma by PSPC1 and TGFβ protein concentrations to add to the melanoma cell culture under conditions of IH or normoxia to evaluate the EMT outcome." (PMID 34359789, 2021). "To evaluate the specific effect of PSPC1 in combination with IH on TGFβ mRNA expression capacity, we used a functional in vitro model with a human melanoma cell line (C-8161) under normoxia and IH conditions." (PMID 34359789, 2021). "Lastly, we studied the correlation between PSPC1 and TGFβ mRNA expression on the melanoma cell line with EMT-TF and CSC-TF transcription factor expression under either IH or normoxia conditions." (PMID 34359789, 2021). "Using the functional model of a melanoma cell line under normoxia and IH, with PSPC1 recombinant protein and human PSPC1 antibody, our data indicated a significant PSPC1 effect on EMT activation through TWIST and SLUG only under IH conditions." (PMID 34359789, 2021). "We have corroborated our hypothesis with a melanoma cell model as a functional model to demonstrate that, under IH, the PSPC1 increases TGFβ expression and promotes EMT, through TWIST and SLUG transcription factors, as well as CSC, although only by means of SOX2." (PMID 34359789, 2021). "To elucidate the effects of circulating PSPC1 protein, we performed an in vitro assay using plasma from patients with OSA in the melanoma cells under normoxia or IH conditions." (PMID 34359789, 2021). "To assess the potential functional impact of PSPC1 and TGFβ activation in patients with OSA when they develop a tumor, we used an in vitro model of melanoma cells, given that melanoma aggressiveness is clearly elevated in these patients." (PMID 34359789, 2021). "We also evaluated the in vitro capability of plasma concentrations of PSPC1 and TGFβ protein to induce CSC-TF expression in melanoma cells, finding that SOX2 might be regulated by both proteins under IH conditions." (PMID 34359789, 2021). "Melanoma cells were cultured with or without PSPC1 protein (rPSPC1) in the presence or absence of a human PSPC1 antibody (α-PSPC1)." (PMID 34359789, 2021).
metastatic tumors (1 paper, 2019). "Moreover, immunohistochemistry (IHC) staining of primary and metastatic tumors showed that PTK6 reversed the effects of PSPC1 on downregulating E-cadherin and upregulating vimentin, β-catenin, c-Myc and Wnt3a." (PMID 31844057, 2019).
ovarian carcinoma (1 paper, 2023). A malignant neoplasm originating from the surface ovarian epithelium. "Taken together, our findings based on the public mRNA database showed that high PSPC1 expression was associated with poor prognosis in breast and ovarian cancer." (PMID 38069409, 2023). "We demonstrated that PSPC1 inhibition enhanced olaparib efficacy in a preclinical model of breast or ovarian cancer with BRCA1/2 mutations compared to olaparib alone, suggesting a promising therapeutic alternative to enhancing PARP inhibitor sensitivity in non-resistance settings." (PMID 38069409, 2023). "Here, we investigated the ability of paraspeckle component 1 (PSPC1), as an additional synthetic lethal partner with BRCA1/2, to enhance olaparib sensitivity in preclinical models of BRCA1/2-mutated breast and ovarian cancers." (PMID 38069409, 2023). "Next, we carried out a cell proliferation assay with PSPC1 siRNA (5 nM) and various concentrations of olaparib in BRCA-mutated breast (BT−474, MDA-MB−436) and ovarian cancer (SNU-251, PEO1) cells." (PMID 38069409, 2023). "Herein, we investigated the synergism of PSPC1 inhibition in combination with olaparib in a preclinical model with PSPC1-expressing, BRCA1/2-mutated breast and ovarian cancer, demonstrating the synergistic anticancer activity of the combination." (PMID 38069409, 2023). "In vitro, the combined olaparib and PSPC1 small interfering RNA (siRNA) exhibited synergistic anti-proliferative activity in BRCA1/2-mutated breast and ovarian cancer cells." (PMID 38069409, 2023). "Similarly, the PSPC1-High group showed shorter OS than PSPC1-Low group in the three data sets of ovarian cancer patients." (PMID 38069409, 2023).
pancreatic cancer (1 paper, 2025). "Outcome of MTT assay demonstrated that PSPC1 silencing could reverse the increased proliferation in pancreatic cancer cells caused by CASC19 overexpression." (PMID 41023804, 2025). "Accompanied with continued research, the novel CASC19/PSPC1/β-catenin axis holds promise as a potential and effective therapeutic target for advanced pancreatic cancer." (PMID 41023804, 2025). "Via successive rescue experiments, it was authenticated that the oncogenic functions of CASC19 in pancreatic cancer are mediated by regulating PSPC1 expression." (PMID 41023804, 2025). "Increased availability of PSPC1, in turn, potentiates nuclear retention of β-Catenin which ultimately triggers pancreatic cancer progression." (PMID 41023804, 2025). "Hereby, we find that CASC19 enhances the PSPC1 protein stability and thus potentiates the PSPC1-mediated nuclear translocation of β-catenin to promote pancreatic cancer progression." (PMID 41023804, 2025). "Our findings elaborate the mechanism of CASC19 mediated tumorigenesis in pancreatic cancer, highlighting the role of PSPC1 in the process." (PMID 41023804, 2025). "Western-blot assay of the rescue experiment showed that upregulated PSPC1 protein level induced by CASC19 overexpression was abolished by PSPC1 siRNA in pancreatic cancer cell MIAPaCa-2." (PMID 41023804, 2025). "PSPC1 protein expression was also high in pancreatic cancer cell lines like that of CASC19 expression." (PMID 41023804, 2025). "Therefore, we conducted CHX assay, MG132 assay and ubiquitination assay which suggests that CASC19 increases PSPC1 protein stability by reducing its ubiquitin-proteasome mediated degradation in pancreatic cancer." (PMID 41023804, 2025). "Therefore, it can be concluded that CASC19 expression did not exert any influence on PSPC1 protein synthesis, rather post-translationally regulate PSPC1 expression by affecting its ubiquitin-mediated degradation and enhance PSPC1 protein stability in pancreatic cancer." (PMID 41023804, 2025). "To further confirm that CASC19-induced oncogenic functions are mediating by PSPC1 in pancreatic cancer, we performed a rescue experiment in CASC19 overexpressing cells with siRNA against PSPC1." (PMID 41023804, 2025). "Thus, the positive correlation of CASC19 and PSPC1 expression and the CASC19/PSPC1/β-catenin axis seems to be a promising therapeutic target in pancreatic cancer treatment." (PMID 41023804, 2025). "Hence, we wanted to investigate whether a similar mechanism is contributing to pancreatic cancer progression, as our findings, so far, showed that high CASC19 expression contributes to more PSPC1 protein stability and more PSPC1 availability in the nucleus." (PMID 41023804, 2025).